SLC25A22 (solute carrier family 25 member 22)
Diseases named in the same sentence as SLC25A22 in open-access papers (continued):
Sharing a sentence is not in itself a finding about the gene and the disease.
cancer (11 papers, 2014 to 2025). A tumor composed of atypical neoplastic, often pleomorphic cells that invade other tissues. "Increased SLC25A22 protein was observed in colorectal cancer tissues and was associated with shorter survival, while transporter knock-down hindered cancer cell proliferation, migration, invasion in vitro and tumor formation and metastasis in vivo." (PMID 31998641, 2019). "Previous research identified SLC25A22 as a key mitochondrial transporter that inhibited ferroptosis in various cancers." (PMID 40298644, 2025). "The present study focused on SLC25A22, a mitochondrial glutamate transporter that has roles in the pathogenesis of diverse cancers." (PMID 40298644, 2025). "One study identified 31 differentially expressed mitochondrial proteins in irradiated cancer cells, such as solute carrier family 25 member 22 (SLC25A22) and peroxisomal biogenesis factor 5 (PEX5)." (PMID 38778409, 2024). "These animal studies further demonstrated the selective negative regulation of SLC25A22 in ferroptotic cancer death in vivo." (PMID 37051693, 2023). "Although previous research showed that SIRT3 and SLC25A22 had important roles in regulating ferroptosis in cancer cells, the present study is the first to identify a correlation and interaction of these two proteins in antagonizing the RSL3-induced ferroptosis of LUAD cells." (PMID 40298644, 2025). "SLC25A22 is able to confer radioresistance to cancer cells by rewiring metabolism." (PMID 38778409, 2024). "Indirectly, SLC25A22 promotes cancer stemness and drug resistance in CRC cells." (PMID 34887764, 2021). "SLC25A22 has a potential to be used as a target for cancer diagnosis of GBC and related therapies." (PMID 30814911, 2019). "Thus, SLC25A22 has a potential to be used as a target for cancer diagnosis of GBC and related therapies." (PMID 30814911, 2019). "SLC25A22, a member of mitochondrial carrier system (MCS) family encoding a mitochondrial glutamate transporter, has been reported to have vital roles in promoting proliferation and migration in cancer." (PMID 30814911, 2019). "First, as a cancer cell, energy is its priority (i.e. functional relation with SLC25A22)." (PMID 25151146, 2014). "Meanwhile, the gene level of matrix metallopeptidase nine and tumor necrosis factor α related to tumor metastasis exhibits a downward trend in SLC25A22-silenced cancer cells, indicating inhibition of GSH synthesis may play a critical role in the treatment of cancer metastasis." (PMID 36970628, 2023). "However, most research about SLC25A22 concentrated on its association neonatal epileptic encephalopathy, so the function of SLC25A22 and its molecular mechanism still remain unclear in malignant tumors." (PMID 30814911, 2019). "Because SIRT3 (a mitochondrial deacetylase) plays critical roles in the regulation of ferroptosis in other cancers, such as GBM, we performed bioinformatic analysis using UALCAN to examine the relationship of the expression of SIRT3 and SLC25A22." (PMID 40298644, 2025). "Although SLC25A22 would be permissive for Asp synthesis, ASNS induction would promote its consumption, suggesting that a dysregulated ASNS expression would be, in fact, a menace for the energetic equilibrium of the cancer cell." (PMID 31998641, 2019). "However, there is little research about SLC25A22 in malignant tumors and no study of effects and mechanism of SLC25A22 in GBC." (PMID 30814911, 2019). "It is also noteworthy that although the other two genes we identified (SLC25A22 and MYEF2) do not possess direct therapeutic utilities at present, they may somehow implicate theoretical clues for cancer therapies." (PMID 25151146, 2014).
metabolic disorders (1 paper, 2025).
SLC25A22 also shares sentences with these, for which no sentence is quoted: keratoconus (2 papers); bipolar disorder (1); breast carcinoma (1); cervical squamous cell carcinoma (1); Fuchs endothelial corneal dystrophy (1); glioma (1); major depression (1); migrating partial seizures of infancy (1); motor neuron disease (1); neurological disorders (1); Obesity (1); oral squamous cell carcinoma (1); ovarian serous adenocarcinoma (1); psychosis (1); Sepsis (1); viral infection (1).